LIF (LIF interleukin 6 family cytokine)
Diseases named in the same sentence as LIF in open-access papers (continued):
Sharing a sentence is not in itself a finding about the gene and the disease.
Obesity (19 papers, 2013 to 2026). Accumulation of substantial excess body fat. "Moreover, these three bacterial strains were significantly associated with certain adipo-myokines related to obesity or inflammation (LIF, FSTL1, FGF21, SPARC, and IL6)." (PMID 39391493, 2024). "Despite representing phenotypic extremes of adiposity, both cancer cachexia and obesity are disease states associated with adipose inflammation, increases in local and circulating levels of IL-6 family cytokines (e.g. IL-6 and LIF), and elevated adipocyte lipolysis." (PMID 35785158, 2022). "With this information in mind, we next hypothesized that different levels of LIF expression in the hypothalamus of mice fed a HFD could affect the predisposition to obesity by regulating both neurotransmitter and inflammatory protein expression." (PMID 28865476, 2017). "Thus, LIF expressed in the hypothalamus emerges as an early determinant of obesity predisposition." (PMID 28865476, 2017). "Comorbidities modulated cytokine expression: diabetes mellitus was linked to reduced LIF and MCP-1, hypertension to decreased LIF and increased IP-10, and obesity to elevated IL-12p70." (PMID 42074217, 2026). "RNA-Seq analysis identified critical pathways modulated by LIF/LIFR signaling in diet-induced obesity mouse models." (PMID 39518071, 2024). "Obesity signals (such as leptin) function as potent inducers of the LIF, the most pleiotropic member of the interleukin-6 family of cytokines." (PMID 39518071, 2024). "The RNA-Seq analysis of xenograft models also confirmed critical pathways modulated by obesity via LIF/LIFR signaling, further elucidating the molecular mechanisms by which obesity influences TNBC progression." (PMID 39518071, 2024). "Obesity-driven signaling functions as a potent inducer of the leukemia inhibitory factor (LIF), the most pleiotropic member of the interleuki-6 family of cytokines." (PMID 39518071, 2024). "On the contrary, the LIF staining was increased in lean patients with 5.3 compared to 3.6 in patients with obesity." (PMID 36710348, 2023). "Cytokines influenced by obesity included LIF (.04 p‐value) and MCP1 (.04 p‐value), which were elevated in the secretome of obese SFs compared to normal weight SFs." (PMID 37006170, 2023). "Members of the TGF-superfamily, like LIF, are known to regulate many aspects of adipocyte development and are involved in the development of obesity and the regulation of energy expenditure." (PMID 37686231, 2023). "Obesity signaling enhances E2 biosynthesis and E2 function as a potent inducer of leukemia inhibitory factor (LIF), which mediate its signaling using a receptor complex comprising LIFR and glycoprotein 130 (gp130)." (PMID 36358818, 2022). "In this study, we examined the utility of EC359 in blocking obesity-mediated signaling that occurs via the LIF/LIFR axis." (PMID 36358818, 2022). "Mechanistic studies suggest that LIF/LIFR signaling plays an important role in obesity-driven EEC progression and the LIFR inhibitor, EC359, has the potential to suppress the tumor progression driven by increased adiposity found in obese patients." (PMID 36358818, 2022). "Collectively, our data support the premise that LIF/LIFR signaling plays an important role in obesity-driven EEC progression and the LIFR inhibitor EC359 has the potential to suppress adipocyte-driven tumor progression." (PMID 36358818, 2022). "These emerging studies suggest the critical role of LIF/LIFR signaling in obesity-induced EC progression." (PMID 34400617, 2021). "Despite the extensive work performed in the evaluation of LIF in cachexia and the regulation of the pituitary function, no previous study has evaluated the role of hypothalamic LIF in obesity." (PMID 28865476, 2017). "The role of LIF/LIFR signaling in obesity-mediated EEC progression remains unclear and is the focus of this study." (PMID 36358818, 2022).
Obesity (continued). "We examined whether the recently developed LIFR inhibitor, EC359, has the ability to block obesity-induced LIF/LIFR-mediated proliferation and signaling in EEC." (PMID 36358818, 2022). "In this study, we examined whether LIF signaling plays a role in the obesity-driven progression of EEC." (PMID 36358818, 2022). "Obesity signals (such as estrogen, leptin) promote EC and function as potent inducers of LIF." (PMID 34400617, 2021). "However, the role of LIF/LIFR signaling in the progression of obesity-driven TNBC remains elusive." (PMID 39518071, 2024). "Hypothalamic LIF may be an important target to prevent the development of diet-induced obesity." (PMID 28865476, 2017). "Myokines affecting sarcopenic obesity include IL-6, IL-10, IL-15, myostatin, insulin-like growth factor (IGF-1), irisin, FGF-21, and leukemia inhibitory factor (LIF)." (PMID 35250869, 2022). "Hence, we speculate that the LIF-LIFR signaling might be impaired in obesity." (PMID 34059769, 2021). "Here, we confirm that obesity affects the inflammatory phenotype of SFs even in non‐load bearing hand joints, with elevated secretion of MCP1, MCP2, MCP3 and LIF, and has a profound but anatomical‐site specific differential effect on their transcriptomic landscape." (PMID 37006170, 2023). "In contrast, obesity triggers the secretion of cytokines involved in osteoporosis, negative vessel remodeling, and inflammation with increased leukemia inhibitory factor (LIF), IL1β, CCL2, leptin, interferon gamma (IFNγ), IL6, and TNFα." (PMID 36010901, 2022). "Because LIF expression was rapidly induced in the hypothalamus of OR mice fed a HFD, we hypothesized that it could play a protective role against the progression to diet-induced obesity." (PMID 28865476, 2017).
prostate carcinoma (19 papers, 2016 to 2026). A carcinoma that arises from epithelial cells of the prostate gland. "It has also been reported that TLR9 expression in prostate cancer, promotes immune evasion through LIF mediated polymorphonuclear MDS activation and amplification." (PMID 41601666, 2026). "A recent experiment has shown how lncRNAs can regulate LIF/STAT3 axis in affecting immune response of prostate cancer cells." (PMID 35773731, 2022). "Patients with prostate cancer had higher levels of LIF within their serum compared to serum of patients with benign prostatic hypertrophy and healthy patients, and serum LIF levels were even more elevated in cases of metastasis to bone." (PMID 35204717, 2022). "LIF in turn is seen to activate signaling cascades that contribute to neuroendocrine differentiation of prostate cancer cells, and the resultant tumor is highly resistant to chemotherapeutics." (PMID 35204717, 2022). "The lncAMPC/LIF/LIFR axis has been shown to play a critical role in prostate cancer metastasis and immunosuppression." (PMID 35608100, 2022). "TLR9 expression in prostate cancer cells promotes immune evasion through LIF (an IL-6 type cytokine and STAT3 activator) mediated polymorphonuclear MDSC amplification and activation." (PMID 36365103, 2022). "As another example, lncAMPC activates LIF/LIFR/Jak1/STAT3 pathway to stable PD-L1 and metastasis-associated genes, thereby contributing to metastasis and immunosuppression in prostate cancer." (PMID 33665192, 2021). "In prostate cancers, another IL-6-type cytokine, leukemia inhibitory factor (LIF), seems to play an important role in the preferential expansion of PMN-MDSCs and their tolerogenic activity." (PMID 29921770, 2018). "Genetic TCGA analysis indicates that LIF is expressed more commonly than IL6 in human prostate cancers." (PMID 29921770, 2018). "In addition, LIF has also been seen to activate polymorphonuclear myeloid-derived suppressor cells (PMN-MDSCs) in mouse models of prostate cancer." (PMID 35204717, 2022). "Importantly, PMN-MDSCs and, to a lesser extent, M-MDSCs isolated from the blood of prostate cancer patients show high surface levels of LIF receptor and respond to LIF stimulation with STAT3 activation and increased T-cell inhibition." (PMID 29921770, 2018). "Therefore, targeting the TLR9/LIF/STAT3 signaling pathway with oligonucleotide-based inhibitors might offer new immunotherapies to treat prostate cancer." (PMID 41601666, 2026). "Therefore, oligonucleotide-based inhibitors (e.g., CpG-STAT3dODN) targeting TLR9/LIF/STAT3 signaling may offer new opportunities for prostate cancer immunotherapy." (PMID 36365103, 2022). "Through polymorphonuclear MDSC proliferation and activation mediated by LIF (an IL-6 type cytokine and STAT3 activator), TLR9 expression in prostate cancer cells facilitates immune evasion." (PMID 40727443, 2025). "ESS2 tends to be highly expressed in prostate cancer patients, and expression levels of some ESS2 target genes, such as LIF, WNT5A, and TGFB1, were significantly correlated with ESS2 levels in prostate cancer patients." (PMID 40362295, 2025). "Among CHD1 target genes, immediate early response 3 (IER3), leukemia inhibitory factor (LIF), and colony stimulating factor 2 (CSF2) were significantly correlated with ESS2 expression in patients with prostate cancer." (PMID 37524814, 2023). "The activation of LIF/LIFR axis stimulates JAK1/STAT3 signaling to preserve PD-L1 expression, leading to immune evasion of prostate cancer." (PMID 35773731, 2022). "Within prostate cancer cells, androgen deprivation therapy was shown to increase expression of the transcription factor ZBTB46, which upregulates LIF expression." (PMID 35204717, 2022). "This study demonstrated that activation of LIF signal transduction and STAT3 signaling promotes neuroendocrine differentiation of prostate cancer treated with androgen deprivation therapy." (PMID 33754118, 2021).
prostate carcinoma (continued). "Thus, TLR9/LIF/STAT3 signaling-targeting oligonucleotide-based inhibitors (e.g., CpG-STAT3dODN) may present novel prospects for prostate cancer immunotherapy." (PMID 40727443, 2025).
myeloid leukemia (16 papers, 2015 to 2025). A clonal proliferation of myeloid cells and their precursors in the bone marrow, peripheral blood, and spleen. "LIF encodes a protein which prevents continued growth of myeloid leukaemia cells by inducing terminal differentiation, although independent removal of LIF did not notably affect model performance." (PMID 34766125, 2020). "Leukemia inhibitory factor (LIF), as an inhibitor of mouse myeloid leukemia cells, could be a possible causative factor and the cause of this syndrome." (PMID 35356245, 2022). "LIF belongs to the IL-6 cytokine family, and is described as a glycoprotein that inhibits M1 myeloid leukemia cell proliferation and induces differentiation." (PMID 36226317, 2022). "Although LIF was named for its ability to induce differentiation of myeloid leukemia cells, studies of LIF in additional diseases and solid tumor types have shown that it has the potential to contribute to many other pathologies." (PMID 35204717, 2022). "Its final name of Leukemia Inhibitory Factor (LIF) is due to early research that discovered its ability to induce differentiation and inhibit proliferation of a myeloid leukemia cell line, but it has since been noted to have many additional functions." (PMID 35204717, 2022). "While LIF induces the differentiation of several myeloid leukemia cells and inhibits their growth, it also promotes tumor progression, metastasis and chemoresistance in many solid tumors." (PMID 25726527, 2015). "For example, LIF maintains the pluripotency of embryonic stem cells, while induces the differentiation of several myeloid leukemia cells and inhibits their growth." (PMID 25726527, 2015). "While early studies showed that LIF induces the differentiation of myeloid leukemia cells, recent studies from others and our laboratory demonstrated that LIF can inhibit cell differentiation and promote proliferation of many types of tumor cell lines." (PMID 25726527, 2015). "The first study about LIF was published in 1969, when Ichikawa Y identified a protein derived from mice that could inhibit the proliferation of myeloid leukemia M1 cells in vitro on various conditioned media." (PMID 35740622, 2022). "LIF was first discovered as a cytokine that induces blast differentiation in myeloid leukemia; however, studies of LIF in other diseases, including cancer, indicate that it may potentially contribute to many other pathologies." (PMID 35626130, 2022). "Early work on LIF revealed its function in inducing the differentiation of myeloid leukemia cells." (PMID 26716902, 2016). "LIF induces the differentiation of several myeloid leukemia cells and inhibits their growth." (PMID 26229239, 2015). "Leukemia inhibitory factor (LIF), a pleiotropic cytokine belonging to the IL-6 superfamily, was initially identified as a factor that induces differentiation in myeloid leukemia cells while simultaneously inhibiting their proliferation." (PMID 40943537, 2025). "Leukemia inhibitory factor (LIF), a member of the interleukin-6 (IL-6) cytokine family, was first recognized for inducing differentiation in myeloid leukemia cells." (PMID 39857986, 2025). "Leukemia inhibitory factor (LIF) was cloned and given its name in 1987 as a suppressor of the proliferation of myeloid leukemia cells in mice." (PMID 35163735, 2022). "Serum LIF levels are significantly lower in patients with myeloid leukemia than in healthy subjects, but LIF levels are significantly greater in bone marrow plasma than peripheral blood plasma regardless of myeloid leukemia status." (PMID 35204717, 2022).
colon carcinoma (14 papers, 2014 to 2025). "Taken together, silencing of STK11/LKB1 in this colon cancer line was associated with local and systemic elevation of LIF, another IL-6 family pro-inflammatory cytokine associated with CC development in colon cancer murine models." (PMID 37092555, 2023). "Blocking LIF in a mouse model of colon carcinoma prevented the initiation and progression of cancer cachexia (e.g., muscle wasting) via the Janus kinase 2–signal transducer and activator of transcription 3 (JAK2–STAT3) pathway." (PMID 38887915, 2024). "In colon cancer, LIF can induce muscle atrophy by activating the JAK/STAT, ERK1/2, and p38 MAPK signaling pathways, resulting in the generation of cachexia." (PMID 35740622, 2022). "Colon cancer cell-derived LIF can regulate the expression of other cytokines, such as granulocyte-colony stimulating factor (G-CSF) and IL-6, to promote tumor progression." (PMID 35740622, 2022). "Interestingly, MSC-1 (a humanized monoclonal antibody that binds to LIF) treatment drove TAMs to obtain antitumor and proinflammatory function in syngeneic colon cancer mouse models." (PMID 38789520, 2024). "LIF is also a key factor that is required for the mouse C26 colon cancer cachexia model." (PMID 35740622, 2022). "Combining the expression trends of these genes in colon cancer and after aspirin treatment, we found that aspirin further upregulated NOX4, CXCL8, CXCL5, LIF, GDF15, and MMP13, while stimulated inhibition of IL2, NCF1, and PTGS1." (PMID 41425852, 2025). "In contrast to colon carcinoma cells, HUWE1 is not required for proliferation ofembryonic stem (ES) cells and deletion of HUWE1 instead delays the decrease of N-MYC levels thatoccurs upon removal of leukemia inhibitory factor (LIF) from the medium (Zhaoet al, 2008)." (PMID 25253726, 2014).
gastric cancer (14 papers, 2018 to 2026). A primary or metastatic malignant neoplasm involving the stomach. "Collectively, these findings identify the LIF/GDF15 axis as a central driver of cancer-associated cachexia in gastric cancer and highlight LIF signaling as a potential therapeutic target." (PMID 41744798, 2026). "Additionally, a study of gastric cancer found that higher levels of LIF and LIFR were associated with increased proliferation, invasion, and metastasis." (PMID 34395259, 2021). "Here, we investigated the association between LIF in regulating GDF15 expression and its relationship with metabolic, inflammatory, and body composition alterations in gastric cancer." (PMID 41744798, 2026). "Mechanistically, experimental models demonstrated that LIF enhances proliferative activity in gastric cancer spheroids and exerts paracrine effects that impair myogenic differentiation and suppress hepatic metabolic gene expression." (PMID 41744798, 2026). "The cell cycle analysis revealed the EC359 in combination with LIF effectively reverses the effect of LIF in a statistically significant manner and decreased the rate of proliferation in gastric cancer cells." (PMID 41163398, 2025). "Leukemia Inhibitory Factor (LIF) has been shown recently to inhibit gastric cancer EMP and stemness in a JAK/STAT dependent manner." (PMID 40994652, 2024). "To determine the correlation between LIF levels and NETs formation, we first tested the LIF levels in gastric cancer patients’ serum and ascites." (PMID 38490994, 2024). "An Interleukin 6 cytokine family member known as Leukemia inhibitory factor (LIF) downregulates Cyclin D1 and upregulates p21 in gastric cancer cells under both in vivo and in vitro conditions." (PMID 36769170, 2023). "Conversely, within gastric cancer cell lines as well as patient-derived xenograft cells and tumourspheres, LIF has been seen to inhibit tumorigenic properties of CSCs." (PMID 35204717, 2022). "Within gastric cancer cells and mouse models, LIF has been seen to be downregulated, and the addition of recombinant LIF or genetic LIF upregulation inhibits proliferation and tumor progression by downregulating cyclin D1, thereby inducing G1 phase arrest." (PMID 35204717, 2022). "Combined with the findings of LIF signaling leading to upstream inhibition of the Hippo pathway in gastric cancer, it is clear that LIF-LIFR-Hippo pathway interactions are highly tumor dependent." (PMID 34395259, 2021). "Summary of studies investigating LIF/LIFR in gastric cancer." (PMID 41163398, 2025). "Indeed, depending upon which signaling pathway is activated (JAK-STAT or Hippo), LIF has been proposed as being pro- or anti-tumoral, as recently demonstrated in gastric cancer stem cell models." (PMID 38137514, 2023). "Therefore, we suspect that the cachexia in pancreatic, colon, esophageal and gastric cancers can be treated by targeting the abnormally high expression of LIF." (PMID 35740622, 2022). "The LIF/LIFR pathway contributing to gastric cancer is complex with context‐dependent pro‐ versus anti‐tumorigenic roles in GC progression, marking it as a significant biomarker and target for future therapies." (PMID 41163398, 2025). "The fact that exposure of MIA PaCa-2 cells to higher concentrations of LIF (25, 50, and 100 ng/mL) promoted a reduction of cell vitality is consistent with the finding that, in some systems, this cytokine exerts direct cytotoxic effects as reported by us and others in gastric cancer cell lines." (PMID 36359879, 2022). "Transcriptomic profiling of paired neoplastic and non-neoplastic gastric mucosa from 61 gastric cancer patients revealed a significant upregulation of both LIF and GDF15 in tumor tissue, with a strong positive correlation between their expression levels." (PMID 41744798, 2026).
gastric cancer (continued). "Expanding the biomarker landscape to include LIF/LIFR, CLDN18.2, FGFR2b, and other emerging targets is critical to advancing personalized treatment strategies and improving survival outcomes for patients with advanced gastric cancer." (PMID 41163398, 2025). "After the surgical treatment of a nude mouse model of gastric cancer cachexia MKN45c185, the initially elevated LIF in plasma is no longer detectable, and cachexia symptoms are eliminated." (PMID 35740622, 2022).